KRAS (KRas proto-oncogene, GTPase)
Diseases named in the same sentence as KRAS in open-access papers (continued):
Sharing a sentence is not in itself a finding about the gene and the disease.
sarcoma (continued). "Yet, exogenous asparagine partially reversed glutamine withdrawal-induced apoptosis in KRAS-driven mouse sarcoma cells." (PMID 33499165, 2021). "Functional genomic screening of KRAS-driven mouse sarcomas was previously employed to identify proliferation-relevant genes." (PMID 32898143, 2020). "Functional genomic screening of KRAS-driven mouse sarcomas was employed to identify actionable proliferation-relevant genes of potential therapeutic applicability." (PMID 32898143, 2020). "YAP1 S127A and KRAS G12V-Cdkn2a null-driven ERMS repress the expression of mostly different gene sets in sarcomas compared to differentiated skeletal muscle, but again approximately 20% (100 genes) of the down regulated genes are identical." (PMID 30353028, 2018). "The rat sarcoma (RAS) genes, including HRAS, KRAS, and NRAS, encode a family of proteins regulating cell growth, differentiation, and apoptosis." (PMID 24782938, 2014). "KRAS and KRas or K-Ras—human species: Kirsten rat sarcoma[virus] gene and protein, respectively." (PMID 40906088, 2025). "Clin Cancer Res 30:4957–4973.This reference is of importance as it defined novel genetic drivers (YAP1, KRAS) and vulnerabilities in high-grade sarcoma models, linking specific oncogenic programmes to sarcoma subtypes and revealing oxidative phosphorylation as a potential therapeutic target." (PMID 41123840, 2025). "KRAS and HRAS were initially identified in cancer cells as the human orthologs of those proto-oncogenes responsible for the initiation of sarcoma in rats infected with two cancer-causing viruses, while NRAS was discovered shortly after by homology with KRAS and HRAS." (PMID 35234863, 2022). "Asparagine depletion strongly impeded KRAS-driven mouse sarcoma cell growth." (PMID 33499165, 2021). "We previously reported on a customized shRNA-based proliferation screen, which tested the contributions of 141 sarcoma-relevant genes, previously identified by transcriptional profiling of genetically engineered mouse sarcomas driven by KRAS(G12v) and CDKN2A deletion." (PMID 32898143, 2020). "KRAS (Kirsten rat sarcoma) mutation is identified as a predictive marker of poor response to EGFR antibodies, and therefore, cetuximab and panitumumab are administered only in KRAS wild type carriers." (PMID 30459532, 2018). "Among disease entities with more than 10 patients tested, no KRAS mutations were found in sarcomas, and adenocarcinomas of stomach and esophagus." (PMID 21829508, 2011). "When these genes were activated in human mesenchymal stem cells (hMSCs), they led to different sarcoma subtypes: YAP1 activation led to undifferentiated pleomorphic sarcoma (UPS), while KRAS activation led to myxofibrosarcoma." (PMID 41123840, 2025). "The Harvey (HMSV) and Kirsten (KMSV) murine sarcoma RNA tumor viruses, named HRAS and KRAS after their respective discoverers, were shown to induce sarcoma and erythroleukemia in rats in the 1960s." (PMID 22928112, 2012). "Beyond these mechanistic constraints, the generalizability of our findings may be influenced by the reliance on a Kirsten rat sarcoma (KRAS)-mutant cellular model (A549), which does not fully capture the genomic heterogeneity of LUAD." (PMID 41556056, 2026). "A candidate set of 141 sarcoma-relevant genes, identified by transcriptional profiling of genetically engineered mouse RMS and non-myogenic sarcomas driven by KRAS(G12v) and CDKN2A deletion, was previously published." (PMID 32898143, 2020).
acute myeloid leukemia (56 papers, 2010 to 2026). Acute myeloid leukemia (AML) is a group of neoplasms arising from precursor cells committed to the myeloid cell-line differentiation. "Regarding theinteraction between SPI1 and KRAS, previous studies have verified their interactionin myeloid leukemia and radiotherapy-associated acute myeloid leukemia." (PMID 41259792, 2025). "NRAS/KRAS mutations have been found in 20–25% of patients with acute myeloid leukemia (AML), 25–30% of patients with juvenile myelomonocytic leukemia (JMML), and 15% of pediatric patients with B- or T-lineage acute lymphoblastic leukemia (ALL)." (PMID 35422065, 2022). "These phenotypes are often seen in chronic myelomonocytic leukemia (CMML), juvenile myelomonocytic leukemia (JMML) and more rarely acute myeloid leukemia (AML) patients harboring KRAS mutations." (PMID 32733479, 2020). "Somatic mutations that lead to constitutive activation of NRAS and KRAS proto-oncogenes are among the most common in human cancer and frequently occur in acute myeloid leukemia (AML)." (PMID 27991934, 2017). "Lastly, the NLRP3 inflammasome contributes to the development of myeloid leukemias, where its activation has been found in chronic myelomonocytic leukemia (CMML), juvenile myelomonocytic leukemia (JMML), and acute myeloid leukemia (AML) patients harboring KRAS mutations." (PMID 35740272, 2022). "Mutations in the RAS gene family (NRAS, KRAS) are critical drivers of late-stage acute myeloid leukemia (AML) progression." (PMID 42087923, 2026). "Mutations in the KRAS and NRAS genes are frequently identified, with mutations in NRAS more frequent than mutations in KRAS, in myeloid disorders (15%–60%), including acute myeloid leukemia (AML), atypical chronic myeloid leukemia (aCML), CMML, and JMML." (PMID 37317963, 2023). "In acute myeloid leukemia (AML), mutations in the RAS gene family, particularly in NRAS and KRAS, are clinically significant." (PMID 39857784, 2025). "It is noteworthy that KRAS overexpression confers an adverse prognosis in cytogenetically normal acute myeloid leukemia (AML) and somatic activation of oncogenic KRAS in hematopoietic cells initiates a rapidly fatal myeloproliferative disorder." (PMID 33522952, 2021). "Genes associated with the pathogenesis of acute myeloid leukemia, such as DNMT3A, NRAS, RUNX1, EZH2, and KRAS, were more commonly mutated in the hypermethylation group." (PMID 30635552, 2019). "Similarly, a notable observation was made regarding the combined effect of mTOR inhibitor and WEE1 inhibitor in both mutant neuroblastoma NRAS- and mutant KRAS-positive acute myelogenous leukemia (AML) cell lines and primary patient samples." (PMID 38231277, 2024). "Notably, in acute myeloid leukemia (AML) cells KRAS, neuroblastoma RAS viral oncogene homolog (NRAS) and ERK2 have been identified as direct targets of miR-181a." (PMID 30081513, 2018). "Although RAS/MAPK pathway mutations affecting NRAS, KRAS, and/or PTPN11 are common in de novo or acute myeloid leukemia (AML)-myelodysplasia-related (MR), BRAF variants rarely occur in AML." (PMID 39596583, 2024). "Apart from FLT3, there are some other recurrent genetic alterations that are also found in other acute myeloid leukemia subtypes, including WT1 (14%), NRAS (10%), KRAS (4%) and MYC amplification (12%)." (PMID 38921185, 2024). "WT1, KRAS, NRAS mutations, FLT3 activation, or Myc trisomy, which are common genetic events in many other subsets of acute myeloid leukemia (AML), may be observed in APL patients." (PMID 29795382, 2018).
acute myeloid leukemia (continued). "HRAS mutations are thus rarely found in myeloid malignancies, whereas mutations leading to oncogenic KRAS or NRAS activation occur in ~ 40% of cases with chronic myelomonocytic leukemia and in 20% of cases of monocytic (FAB classes M4 and M5) forms of acute myeloid leukemia (AML)." (PMID 30323311, 2019). "Mutations in the RAS/MAPK signaling pathway are recurrent in acute myeloid leukemia (AML), primarily involving NRAS and KRAS." (PMID 42297916, 2026).
bladder cancer (56 papers, 2008 to 2026). "TaqMan arrays can be used to find mutations in genes, like the EGFR and KRAS genes, that are commonly changed in bladder cancer cases." (PMID 39678505, 2024). "The KRAS mutation has been found to be present in a small percentage of primary bladder adenocarcinomas, is associated with the onset and prognosis of bladder cancer and can be used as a biomarker for bladder cancer surveillance and efficacy evaluation." (PMID 36686734, 2022). "In the same manner, pesticide exposure can induce different genetic damages, affecting the KRAS gene associated with an increased risk of bladder cancer." (PMID 34444445, 2021). "Colon and bladder cancer cells with KRAS mutation are resistant to AZD5363, although accompanied by coincident PIK3CA mutations." (PMID 32194423, 2020). "A prospective study has reported an association between the presence of the codon 12 KRAS mutation in plasma of apparently healthy individuals and the development of bladder cancer after a follow-up period." (PMID 28199989, 2017). "This implies that Sh presence may upregulate KRAS, increasing the risk of developing bladder cancer." (PMID 39250522, 2024). "Furthermore, 20% of the dysplastic bladder lesions were found to have a KRAS gene mutation, which is commonly found in bladder cancers." (PMID 39250522, 2024). "RAS is the most frequently mutated oncogene in bladder cancer, with KRAS, HRAS, and NRAS involved." (PMID 39678505, 2024). "Additionally, a recent study revealed the great potential of urine exoDNA to detect somatic mutations, such as KRAS, compared to exoDNA from serum samples in bladder cancer." (PMID 36830940, 2023). "KRAS mutations, although found in a lower percentage (11.5%) of bladder cancers, are assuming a relevant position since the detection of KRAS mutations in conjunction with the previous alterations could improve the sensitivity of a biomarker panel." (PMID 31921291, 2019). "Uromonitor is a urine-based biomarker test for bladder cancer recurrence detection that screens hotspot mutations in the TERT, FGFR3, and KRAS genes." (PMID 40282460, 2025). "In this study, the differentially expressed proteins involved in the actin cytoskeleton signaling pathway were mostly upregulated in bladder cancer, including KRAS and MAPK1 proteins involved in the ERK/MAPK signaling pathway." (PMID 38410113, 2024). "In contrast, 27.2% of HRAS-mutant bladder cancers carried a co-altered MAPK mutation compared to 23% and 44% of KRAS and NRAS, respectively." (PMID 37503077, 2023). "Previous study showed that mutations in HRAS, KRAS, and NRAS exist in approximately 30% of human cancers, with HRAS mutations being more common in bladder cancer compared to the other two67." (PMID 37704624, 2023). "The KEGG bladder cancer pathway activation in poor prognosis CRCs was mostly due to increased expression of functional nodes HRAS/KRAS/NRAS, ARAF/BRAF/RAF1, MAPK1/MAPK3, and RPS6KA5." (PMID 36316649, 2022). "To explore the transcriptional response to RS-inducing drugs in another cell line, we included the KRAS mutant UM-UC-3 bladder cancer cell line in our transcriptomic analysis." (PMID 35393546, 2022). "We analyzed the performance of Uromonitor® + KRAS in the initial diagnosis of bladder cancer in comparison to cystoscopy and/or cytology." (PMID 31921291, 2019). "In the presence of silibinin, KRAS overexpression restored cell proliferation and invasion which were suppressed by silibinin in bladder cancer cells." (PMID 29190895, 2017). "We have therefore developed a multiplex mutation assay for the detection of the most frequently occurring HRAS, KRAS, and NRAS mutations in bladder cancer." (PMID 21072204, 2010). "In this study, we found that the KRAS protein was upregulated in bladder cancer, suggesting that the protein may promote the proliferation and differentiation of bladder cancer cells by transducing tyrosine kinase signaling." (PMID 38410113, 2024).
bladder cancer (continued). "Additionally, KRAS-12 was observed in bladder cancer, and KRAS-13 was identified in uterine corpus (UCEC)." (PMID 38473427, 2024). "To further improve Uromonitor® test performance, we analyzed a subset of samples (Uromonitor® + KRAS follow-up cohort) for another oncogene activated in bladder cancer, KRAS hotspot alterations, and compared follow-up recurrence detection to routinely used surveillance methods." (PMID 31921291, 2019). "With the inclusion of KRAS hotspot mutation screening together with Uromonitor®, this preliminary data presents this noninvasive approach as a true alternative to cystoscopy for NMIBC follow-up or even as a population screening and/or initial diagnosis for bladder cancer." (PMID 31921291, 2019). "Zhai and Xu found that the suppression of miR-126 mediated by the overexpressed lnc-ATB increases KRAS mRNA and protein, consequently activating PI3K/AKT and mTOR pathways in bladder cancer." (PMID 33498521, 2021). "We also identified the RAS oncogene family (KRAS, NRAS, and HRAS) as a bladder cancer stimulus factor." (PMID 34234808, 2021). "Among the bladder cancer cell lines studied in our work, only UMUC-3 expresses an oncogenic mutant of KRas, namely KRasG12C." (PMID 34944949, 2021). "This study has discovered that miRNA-1184 interacts with KRAS, NRAS, and HRAS coding genes, thereby regulating their effect in bladder cancer." (PMID 34234808, 2021). "This pathway is activated in around 40% bladder cancer cases (FGFR3: > 10%, EGFR:> 10%, ERBB2:~ 10%, ERBB3:~ 10%, NRAS/HRAS/KRAS:~ 10%, PTEN: ~ 10%, AKT3:~ 10%)." (PMID 31665050, 2019). "Guanidino anthratiophenediones have been previously shown to stabilize G4 structures in vitro in promoter and in 5′-UTR mRNA of KRAS, inhibit gene transcription, reduce p21HRAS protein levels, and inhibit proliferation of bladder cancer cells but not through induction of apoptosis." (PMID 25853628, 2015).
mucinous tumors (55 papers, 2008 to 2025). "HPCs 12, 14, and 38 contained mucinous tumors tissue, which has also been linked to KRAS mutational burden." (PMID 40057490, 2025). "The prevalence of pathogenic KRAS or GNAS variants is high in mucinous neoplasm (approximately 2/3 of mucinous neoplasms contain a pathogenic variant of either KRAS, GNAS or both 38), making KRAS and GNAS variants reliable molecular markers." (PMID 33536452, 2021). "The sixth resected case was diagnosed as PDAC after negative conventional cytology and detection of a pathogenic variant of KRAS, which was at least indicative of mucinous neoplasm." (PMID 33536452, 2021). "KRAS mutations (preferentially observed in exon 2) seem to have a pivotal role in the development of appendiceal mucinous neoplasms." (PMID 33712927, 2021). "A concordant KRAS mutation (c.35G > A p.G12A) was identified in both mucinous tumors and mural nodules." (PMID 32290854, 2020). "The present study demonstrates that dual MEK‐PI3K inhibitor therapy (trametinib plus pictilisib) reduces mucinous tumor growth in patient‐derived ex vivo and in vivo models of KRAS mutated mucinous colon/appendix cancer." (PMID 31958897, 2020). "For instance, serous borderline tumors or low-grade serous ovarian carcinoma (LGSOC) are characterized by frequent KRAS or BRAF mutations while mucinous tumors carry KRAS mutations and endometrioid ovarian tumors harbor PTEN mutations." (PMID 30478449, 2019). "Among the ovarian tumors, KRAS mutations were more frequent in mucinous tumors than in other types (7/8 vs. 2/14; P = 0.0015 by Fisher’s exact test)." (PMID 29464067, 2018). "Our studies thus provide a rational basis for MEK- and PI3K-targeted combination therapy for not only KRAS mutant MCA but also for other related mucinous neoplasms that overproduce MUC2 and have a high rate of KRAS mutations such as pseudomyxoma peritonei." (PMID 28640835, 2017). "We confirmed the high prevalence of FOXL2 and KRAS mutations in granulosa cell tumors and in mucinous tumors, respectively." (PMID 28852190, 2017). "Other predictors of higher MSI rate were advanced stage, mucinous tumor and KRAS mutation (all P value ≤ 0.01)." (PMID 27120810, 2016). "KRAS mutations were frequent in men, older patients, smokers, adenocarcinomas, mucinous tumor types, large-sized tumors, poorly differentiated tumors, and tumors with a solid pattern, consistent with previous reports." (PMID 26992209, 2016). "Our re-sequencing efforts confirmed KRAS mutations to be the most frequent molecular alteration amongst mucinous tumors, appearing more common in borderline malignancies over carcinomas (92.3 % versus 64.9 %, respectively; Fisher exact p = 0.0157)." (PMID 25986173, 2015). "KRAS mutations have been described in up to 68% of cases of mucinous ovarian cancer, while present in only 5% of non-mucinous tumors." (PMID 27231561, 2015). "All fallopian tube samples were KRAS wild-type, and KRAS mutations were only seen in two of three corresponding mucinous tumours." (PMID 23800114, 2013). "However, one study showed that low-grade mucinous neoplasms were associated with concurrent KRAS proto-oncogene, GTPase (KRAS), and GNAS complex locus (GNAS) mutations." (PMID 37566041, 2023). "Although both CMS3 and mucinous tumors are known to be associated with KRAS mutations, the exact underlying mechanism for this association remains unclear." (PMID 36293565, 2022). "Moreover, KRAS mutations have been identified in a high proportion of disseminated mucinous neoplasms." (PMID 33712927, 2021). "Instead, the majority of mucinous tumors exhibit either HER2 amplification or KRAS mutation." (PMID 27231561, 2015). "KRAS mutations were detected with high frequency in cases with predominantly mucinous tumors." (PMID 25760072, 2015).